GLIS3 (GLIS family zinc finger 3)
Diseases named in the same sentence as GLIS3 in open-access papers (continued):
Sharing a sentence is not in itself a finding about the gene and the disease.
type 2 diabetes (continued). "The Glis3-Manf axis has been identified as being pivotal to the relative fragility or robustness of stressed islets, potentially operating in both type 1 and type 2 diabetes." (PMID 36291702, 2022). "Another example is Glis3, which is a transcription factor and plays a key role in neonatal diabetes, type 1 and type 2 diabetes." (PMID 34745232, 2021). "Separately, a novel heterozygous mutation was identified in the N-terminal region (c.589G>T; Asp197Tyr) of GLIS3, in a Turkish patient diagnosed with maturity onset diabetes of the young (MODY)." (PMID 34943978, 2021). "A recent analysis suggested that the same genetic variant alters risk of both type 1 and type 2 diabetes in five regions, near CENPW, CTRB1/BCAR1, GLIS3, BCL11A and THADA." (PMID 33830302, 2021). "The GLIS3-rs7034200 exhibited larger effect size on type 2 diabetes compared to that in white Europeans, and its contribution to type 2 diabetes risk is mainly mediated through impaired beta-cell function." (PMID 21747906, 2011). "In the present study of Chinese Hans, GLIS3-rs7034200 was significantly associated not only with fasting glucose and HOMA-B, but also with type 2 diabetes risk." (PMID 21747906, 2011). "In whites of European ancestry, GLIS3 was identified as in GWA studies for fasting glucose and beta-cell function as estimated by HOMA-B, yet the locus was also nominally associated with type 2 diabetes." (PMID 21747906, 2011). "More recently, another study in a case-control sample of Chinese also replicated the associations of DGKB, MADD, GLIS3, PROX1 and IGF1 with type 2 diabetes and/or glycemic traits." (PMID 21747906, 2011). "In this population-based cohort of Chinese Hans, we confirmed the associations of GLIS3-rs7034200 with fasting glucose and beta-cell function as estimated by HOMA-B, as well as with risk of type 2 diabetes and/or IFG." (PMID 21747906, 2011). "SNPs from GIPR, TCF7L2, CRY2, GLIS3 and SLC30A8 were also associated with type 2 diabetes (p = 0.0487∼2.0×10−8)." (PMID 21103350, 2010). "The transcription factor GLI-similar 3 (GLIS3) rs7034200C/A and adrenergic receptor beta 3 (ADRB3) rs4994T/C (Trp64Arg) polymorphisms are closely related to glucolipid metabolism, insulin resistance, obesity, and increased risk of type 2 diabetes." (PMID 41272565, 2025). "We found an equal number of female and male participants carrying a P/LP GLIS3 variant, either with type 2 diabetes or not (data not shown)." (PMID 38051360, 2024). "Among patients with type 2 diabetes, we observed a higher prevalence of rare GLIS3 missense variants (2.5%) compared to non-diabetic individuals (1.8%) (odds ratio of 1.37 (interquartile range:1.01–1.88, p = 0.04))." (PMID 31415576, 2019). "We also provide evidence for the first time in South Asians that alleles of SNPs in GLIS3 and ADCY5 may confer risk of type 2 diabetes." (PMID 21949744, 2011). "In conclusion, our results confirmed the associations of GLIS3-rs7034200 with fasting glucose and risk of type 2 diabetes, and we also observed a moderate significant association between CRY2-rs11605924 and combined IFG/type 2 diabetes in Chinese Hans." (PMID 21747906, 2011). "We confirmed the associations of GLIS3-rs7034200 with fasting glucose (beta = 0.07 mmol/l, P = 0.03), beta cell function (HOMA-B) (beta = −3.03%, P = 0.009), and type 2 diabetes (OR [95%CI] = 1.27 [1.09–1.49], P = 0.003) after adjustment for age, sex, region and BMI." (PMID 21747906, 2011). "We found that the expected effect (β = 0.15), estimated by multiplying the magnitude of the association between GLIS3-rs7034200 and HOMA-B and of the association between HOMA-B and type 2 diabetes risk, was comparable to the observed effect (β = 0.24, P(exp/obs) = 0.53)." (PMID 21747906, 2011). "Since HOMA-B explained only 63% of the association between GLIS3-rs7034200 and type 2 diabetes, additional unknown mechanisms independent of insulin release might also mediate the association." (PMID 21747906, 2011).
type 2 diabetes (continued). "The ROCAUC values of GLIS3-rs7034200 and CRY2-rs11605924 for the discrimination of type 2 diabetes were 0.543 and 0.511 respectively." (PMID 21747906, 2011). "We showed SNPs from seven loci, including GIPR, TCF7L2, MADD, CRY2, GLIS3, PROX1 and SLC30A8, had an effect on type 2 diabetes in our samples." (PMID 21103350, 2010). "Of the 132 type 2 diabetes Knowledge Portal effector genes, we identified 18 (14%) as candidate effector genes for at least one phenotype, including ABCC8, KCNJ11, NKX2–2, G6PC2, PAM, HNF4A, SLC30A8, RFX6, PCSK1, and GLIS3." (PMID 37333221, 2023). "However, we did not observe a difference in the relative expression of Glis3 isoforms between wild-type and db/db mice, a model for Type 2 diabetes." (PMID 41369402, 2025). "We did not replicate the finding that the chromosome regions near CENPW, GLIS3, BCL11A or THADA co-localised between type 1 and type 2 diabetes (H4PP CENPW=0.12, GLIS3=0.29, BCL11A=0.28, THADA not examined as no type 1 diabetes association existed in the region [FDR=0.07])." (PMID 33830302, 2021).
hypothyroidism (12 papers, 2007 to 2025). Abnormally low levels of thyroid hormone. "Loss-of-function mutations in GLIS3 are causally linked to neonatal diabetes and hypothyroidism (NDH) in humans, matching the phenotype observed in mice with deletions of Glis3." (PMID 41369402, 2025). "Although the present research on the mechanism underlying the defects in PC that influence thyroid function and cause hypothyroidism is limited, it can be inferred that PC interact with Glis3 via the signaling pathway and result in thyroid dysfunction." (PMID 38260150, 2023). "Deficiency in GLIS3 protein is linked to insufficient follicular cell proliferation, low TH production, and hypothyroidism in humans." (PMID 34237030, 2021). "One patient of GLIS3 mutation with a deletion of exons 1–2, hypothyroidism was identified on day four of life with TSH levels >150μIU/l and T4 at 4.3pmol/l." (PMID 28253873, 2017). "Very recently, mutations in Glis3 (another transcription factor) were found to explain a syndrome which associated neonatal diabetes, hypothyroidism, congenital glaucoma, kidney cysts and hepatic fibrosis." (PMID 17349054, 2007). "Genetic aberrations in human GLIS3 are associated with a syndrome that is characterized by neonatal diabetes and hypothyroidism (NDH) and may include polycystic kidney disease, glaucoma, and mild mental retardation depending on the nature of the mutation." (PMID 27270601, 2016). "Genetic aberrations within the GLIS3 locus are associated with a rare syndrome characterized by neonatal diabetes and hypothyroidism and may include polycystic kidney disease, hepatic fibrosis, glaucoma, and mild mental retardation depending on the nature of the mutation." (PMID 26147758, 2015). "Here we report a patient with a homozygous deletion in the GLIS3 gene who, in addition to neonatal diabetes, hypothyroidism and further previously reported organ manifestations, suffered from hyporegenerative anemia and megalocornea without elevated intraocular pressure." (PMID 33935973, 2021). "Although hypothyroidism is associated with GLIS3 variants, the absence of consistent pathological features in patients makes unclear the identification of a causative mechanism." (PMID 30555422, 2018). "As well as the majority of patients with homozygous GLIS3 mutations, GLIS3-deficient mice (GLIS3-/-), who present a similar phenotype with impaired pancreatic islet development, polycystic kidney disease and hypothyroidism, did not exhibit overt congenital hematological problems." (PMID 33935973, 2021). "In addition to neonatal diabetes, hypothyroidism, cholestasis and kidney cysts, the boy presented congenital hyporegenerative anemia (Hb at day one: 11.8 g/dl, Hb minimum around day 34: 6.5 g/dl), which has not been reported in individuals with homozygous GLIS3 mutations to date." (PMID 33935973, 2021). "A similar phenotype, including neonatal diabetes, polycystic kidney disease, and hypothyroidism, is observed in mice lacking functional Glis3." (PMID 26147758, 2015).
polycystic kidney disease (12 papers, 2009 to 2026). A usually autosomal dominant and less frequently autosomal recessive genetic disorder characterized by the presence of numerous cysts in the kidneys leading to end-stage renal failure. "Deficiency in the transcription factor (TF) GLI-Similar 3 (GLIS3) in humans and mice leads to the development of polycystic kidney disease (PKD)." (PMID 39505148, 2024). "Mutations and a large deletion in the 5-UTR region of the GLIS3 gene have been reported in children with neonatal diabetes mellitus and congenial multiple malformation including polycystic kidney." (PMID 23349908, 2013). "Both Glis3 and Itch have been implicated in, respectively, promoting or inhibiting osteoblast differentiation and both proteins have been linked to the transcriptional mediator TAZ, which has been linked to the development of polycystic kidney disease as we reported for Glis3." (PMID 26147758, 2015). "The transcription factor Gli-similar 3 (Glis3) plays a critical role in the generation of pancreatic ß cells and the regulation insulin gene transcription and has been implicated in the development of several pathologies, including type 1 and 2 diabetes and polycystic kidney disease." (PMID 26147758, 2015). "As for NDH patients, the Glis3 mutant mice also developed polycystic kidney disease, pointing up the role of Glis3 in the maintenance of the normal renal function." (PMID 30555422, 2018). "Deficiency in GLI-similar 3 (GLIS3) in humans and mice causes polycystic kidney disease (PKD)." (PMID 41826646, 2026). "Our study suggests that GLIS3 may have a protective role in the postnatal kidney against cyst formation and that targeting GLIS3 signaling may offer therapeutic opportunities in the management of polycystic kidney disease." (PMID 39505148, 2024). "GLIS3 has been indicated to act a significant part in preserving the natural structure and function of the kidney as part of transcription regulatory networks, and GLIS3 mutant develops polycystic kidney disease." (PMID 36967395, 2023). "The patient with GLIS3 mutation showed hepatic dysfunction without liver fibrosis and polycystic kidney disease at onset but eventually died of liver and kidney failure 1 year later in a local hospital." (PMID 26839896, 2016).
glaucoma (8 papers, 2007 to 2026). Increased pressure in the eyeball due to obstruction of the outflow of aqueous humor. "In mouse models, Glis3 is expressed in a dynamic pattern during eye development, initially in the dorsal optic vesicle and subsequently in the lens and the retina, which supports the presentation of glaucoma in our patients and previous patients with GLIS3 mutations." (PMID 26259131, 2015). "Similarly, patients with GATA6 mutations require regular cardiac evaluations, while those with GLIS3 defects must be monitored for glaucoma and thyroid dysfunction." (PMID 41614934, 2026). "However, recognizing the specific genetic etiology is critical for predicting and managing the associated multi-system comorbidities, such as monitoring for glaucoma in GLIS3 patients or cardiac defects in GATA6 carriers." (PMID 41614934, 2026).
MODY (8 papers, 2018 to 2024). "In the first phase of the study, whole-exome sequencing was performed on 21 probands with a MODY phenotype and five of their first-degree relatives (three with a MODY phenotype) for analysis of the GLIS3 mutation spectrum." (PMID 29606121, 2018). "We screened GLIS3 gene sequences among patients with MODY to identify probably pathogenic variants by whole-exome sequencing." (PMID 29606121, 2018). "Previously, some of GLIS3 gene polymorphisms have been shown to be associated with the development of MODY." (PMID 29606121, 2018). "The aim of this study was identification of probably pathogenic variants of GLIS3 in patients with MODY using a whole-exome sequencing approach and estimation of the frequency of rs806052, rs143051164, and rs149840771 in a Russian population and DM2 patients." (PMID 29606121, 2018). "The spectrum of GLIS3 gene polymorphism in patients with a MODY phenotype was identified by the whole-exome sequencing method." (PMID 29606121, 2018). "Consequently, recent studies identified RFX6 as a novel MODY gene and WFS1, PPARG, and GLIS3 have recently been proposed as potential candidates for these rare MODY forms." (PMID 34079523, 2021). "Other rare variants found in a South Indian population that could potentially play a role in MODY pathogenesis are EIF2AK3, GLIS3, HADH, and PTF1A." (PMID 39201476, 2024). "The results of genotyping of the Caucasian group and patients with carbohydrate metabolism disorders allow us to suggest that rare SNVs rs806052, rs143051164, and rs149840771 of the GLIS3 gene do not take part in the pathogenesis of MODY and DM2 in Russia." (PMID 29606121, 2018). "Whole-exome sequencing did not reveal new SNVs in GLIS3 of patients with MODY in Russia." (PMID 29606121, 2018).
type 1 diabetes (8 papers, 2011 to 2025). "Multiple single nucleotide polymorphisms (SNPs) in GLIS3 have been associated with the genetic predisposition of several diseases, including type 1 diabetes, T2D, neurological disorders, and glaucoma, in diverse populations." (PMID 41272565, 2025). "Genome-wide association studies have shown that multiple SNPs in GLIS3 are closely associated with several pathologies, including T2D and type 1 diabetes, in several populations." (PMID 41272565, 2025). "A protein–protein interaction network was linked to type 1 diabetes-associated genes with differentially expressed seroconversion genes, revealing direct interactions with ERBB3 and GLIS3, two type 1 diabetes susceptibility genes." (PMID 32797243, 2020). "Rare functional mutations within the GLIS3 gene lead to a syndrome of neonatal diabetes and congenital hyperthyroidism, and the rs7020673 SNP within the gene is robustly associated with type 1 diabetes." (PMID 21949744, 2011). "In a non-obese mouse model for type 1 diabetes, SNPs in Glis3 have been associated with increased beta cell unfolded protein response and apoptosis." (PMID 28931935, 2017).
Hyperglycemia (7 papers, 2013 to 2024). An increased concentration of glucose in the blood. "GLIS3 deficiency significantly reduces the generation of endocrine cells, particularly β-cells, causing severe hyperglycemia in both mice and humans." (PMID 34943978, 2021). "Additionally, beta cell-specific KO of Glis3 in adult mice results in the development of hyperglycemia due to an almost total loss of insulin production." (PMID 26147758, 2015). "Glis3 global knockouts display decreased gene expression and staining for all endocrine hormones, and pups die within the first 10 days, likely due to hyperglycemia." (PMID 34943978, 2021). "Mafa expression appears to be directly regulated by Glis3 within pancreatic islets, in line with the observed decreased expression of Mafa in β-cells from Glis3 knockout mice, and rising hyperglycemia." (PMID 34943978, 2021). "TAM-mediated beta cell-specific inactivation of Glis3 in adult mice downregulates insulin expression, leading to hyperglycaemia and subsequently enhanced beta cell apoptosis." (PMID 23197416, 2013). "We demonstrated that in contrast to ubiquitous Glis3KO mice, pancreatic insulin expression and non-fasting blood glucose levels were not changed in Glis3-Pax8Cre mice confirming that these mice did not develop hypoinsulinemia/hyperglycemia." (PMID 38281222, 2024).
neonatal diabetes mellitus (7 papers, 2009 to 2024). Neonatal diabetes mellitus presents as hyperglycemia, failure to thrive and, in some cases, dehydration and ketoacidosis which may be severe with coma, in a child within the first months of life. "CH, combined with neonatal diabetes mellitus, is caused by mutations in the TF GLIS3 gene." (PMID 38919955, 2024).
congenital glaucoma (6 papers, 2015 to 2026). "Sensory: WFS1 is linked to optic atrophy and deafness; GLIS3 to congenital glaucoma; PAX6 to aniridia." (PMID 41614934, 2026). "The absence of pancreatic and thyroid GLIS3 transcripts in the 2 families with deletions resulted in neonatal diabetes and hypothyroidism and the absence of an eye-specific transcript in 1 family resulted in congenital glaucoma." (PMID 26259131, 2015).
Insulin resistance (6 papers, 2011 to 2025). Increased resistance towards insulin, that is, diminished effectiveness of insulin in reducing blood glucose levels. "Our findings imply that the GLIS3 rs7034200C/A genetic variant contributes to oxidative stress, insulin resistance, and glucolipid metabolism disorders." (PMID 41272565, 2025). "We further demonstrated that the GLIS3 rs7034200C/A variant contributes to insulin resistance, glucolipid metabolic disorders, and oxidative stress imbalance in the study population, thus may be involved in the pathophysiology of GDM." (PMID 41272565, 2025). "Furthermore, the GLIS3 rs7034200C/A variant significantly affected oxidative stress, insulin resistance, and glucolipid metabolism." (PMID 41272565, 2025). "GLIS3 expression is required for compensatory pancreatic cell proliferation and mass expansion in response to insulin resistance." (PMID 35246208, 2022).
Renal cyst (6 papers, 2009 to 2026). A fluid filled sac in the kidney. "Glis3 deficiency in humans and mice is also associated with typical ciliopathy phenotypes, including cystic kidney disease, suggesting that both Glis2/NPHP7 and Glis3 are required for normal ciliary function and/or ciliary signaling." (PMID 26083374, 2015). "Loss of pc/GLIS3 function in medaka and humans results in renal cyst formation, implying that GLIS3 is functionally equivalent in these animals." (PMID 19609364, 2009). "In conclusion, we identified the medaka pc gene, an ortholog of human GLIS3, as a gene causing cystic kidney." (PMID 19609364, 2009). "Moreover, the co-occurrence of renal cysts in GLIS3 deficiency highlights the gene’s role in maintaining renal tubular architecture, necessitating regular renal ultrasound monitoring." (PMID 41614934, 2026). "Kidneys of Glis3-deficient mice exhibit several features of metabolic reprogramming, a bioenergetic environment that contributes to abnormal renal cell proliferation and progression of renal cyst formation." (PMID 39505148, 2024). "Although these features of metabolic reprogramming observed in Glis3-deficient kidneys may contribute to renal cystogenesis, further studies are needed to determine the extent to which it contributes to the initiation and progression of renal cyst formation." (PMID 39505148, 2024). "One allele, NDH1, which harbors a single base pair insertion that causes a frameshift mutation and a truncated protein, cause cystic kidney, while the other two alleles, NDH2 and NDH3, which have large deletions in the GLIS3-flanking region, do not." (PMID 19609364, 2009).
breast carcinoma (5 papers, 2016 to 2023). "Our previous GSEA of melanoma cell lines revealed association of GLIS3 with breast cancer (the same gene set that showed upregulation of PXDN), supporting its role in multiple tumour types." (PMID 27172792, 2016). "GLIS3 deregulation was also associated with liver, thyroid, and breast cancer." (PMID 34715892, 2021). "Interestingly, overexpression of GLIS3 has already been reported in breast cancer tissue." (PMID 35158735, 2022). "However, the literature does not support a tumor suppressing role for the GLIS3 transcription factor gene, as GLIS3 reportedly exerted tumor-promoting activities in melanoma and breast cancer." (PMID 38045004, 2023). "However, further in vitro experiments, which were beyond the scope of the present translational study, will be needed in order to confirm the putative role of GLIS3 and ZNF658 in FNTB’s transcriptional regulation and its effects on oncogenic RAS signalling in breast cancer." (PMID 35158735, 2022).